NRN1 (neuritin 1)
Description:
Promotes neurite outgrowth and especially branching of neuritic processes in primary hippocampal and cortical cells.
Synonyms: NRN; dJ380B8.2
Tractability: Antibody: UniProt places it where antibodies can reach, with high confidence; its Gene Ontology location is reachable by antibodies, with high confidence; UniProt predicts a signal peptide or a membrane-spanning region.
Gene: Protein-coding gene on chromosome 6 (5,997,999 to 6,008,688, reverse strand). Ensembl gene ENSG00000124785.
Subcellular location: Cell membrane; Synapse
Pathways (Reactome):
Metabolism of proteins: Post-translational modification: synthesis of GPI-anchored proteins
Gene Ontology:
Molecular function: identical protein binding
Biological process: neuron projection extension; nervous system development; presynaptic modulation of chemical synaptic transmission; regulation of synapse maturation
Cellular component: extracellular region; plasma membrane; AMPA glutamate receptor complex; glutamatergic synapse; presynapse; synapse
Genetic constraint (gnomAD): Loss-of-function variants: 4 observed, 14.76 expected, observed/expected ratio (o/e) 0.27, 90% interval 0.13 to 0.62. The upper end of that interval is the gene's LOEUF score, 0.62, which puts it in group 2 of 6, group 1 being the genes least tolerant of losing a copy. Missense variants: 133 observed, 192.38 expected, observed/expected ratio (o/e) 0.69, 90% interval 0.6 to 0.8. Synonymous variants: 85 observed, 87.54 expected, observed/expected ratio (o/e) 0.97, 90% interval 0.81 to 1.16.
Homologues: Orthologues: dog NRN1 (99% identical), mouse Nrn1 (97% identical), guinea pig NRN1 (96% identical), chimpanzee NRN1 (88% identical), rat Nrn1 (88% identical), macaque NRN1 (87% identical), pig NRN1 (87% identical), rabbit NRN1 (84% identical), tropical clawed frog nrn1 (68% identical), zebrafish nrn1a (68% identical), zebrafish nrn1b (52% identical). Paralogues in human: NRN1L (32% identical).
Diseases named in the same sentence as NRN1 in open-access papers:
NRN1 is named in the same sentence as 64 diseases in open-access papers, as found by Europe PMC text mining. Sharing a sentence is not in itself a finding about the gene and the disease. The quoted sentences say what the papers report.
Alzheimer disease (6 papers, 2019 to 2026). A progressive, neurodegenerative disease characterized by loss of function and death of nerve cells in several areas of the brain leading to loss of cognitive function such as memory and language. "NRN1 polymorphisms are known risk factors for schizophrenia, bipolar disorders, and Alzheimer’s disease." (PMID 37192378, 2023). "In Alzheimer’s disease, miR-194 targets Nrn1 and reduces the PI3K/Akt signalling pathway activity, promoting hippocampal neuronal apoptosis." (PMID 34052838, 2021). "miR-194 accelerated apoptosis of hippocampal neurons in Alzheimer’s disease by targeting the inhibition of Nrn1 and decreasing PI3K/Akt signaling pathway activity." (PMID 31010100, 2019). "Further in-depth research indicated that miR-194 accelerated apoptosis of hippocampal neurons in Alzheimer’s disease by targeting the inhibition of Nrn1 and decreasing PI3K/Akt signaling pathway activity." (PMID 31010100, 2019). "•Computational analysis links NRN1 with cognitive resilience to Alzheimer’s disease." (PMID 37024090, 2023).
melanoma (6 papers, 2017 to 2025). A malignant, usually aggressive tumor composed of atypical, neoplastic melanocytes. "Recently, aberrant methylation of the NRN1 gene promoter region has been associated with tumor development, such as gastric cancer and melanoma." (PMID 36765573, 2023). "Recently, several studies have shown that aberrant methylation in the promoter region of the nrn1 gene is associated with the development of tumors (e.g., gastric cancer and melanoma)." (PMID 35884598, 2022). "Studies utilizing melanoma cell lines have demonstrated that NRN1 promotes melanoblast proliferation, enhances cell–cell adhesion, and facilitates cell migration and angiogenic processes." (PMID 41425077, 2025). "Clinically, serum NRN1 levels are significantly elevated in patients with melanoma compared to those with non-melanoma skin cancers." (PMID 41425077, 2025). "NRN1 can be found in significantly increased levels in the serum of melanoma patients with brain metastases." (PMID 38705997, 2024). "Our data showing a downregulation of Notch signaling along the N1ICD-HES1 axis due to high NRN1 expression astonishingly suggest a tumour-suppressive role of the NRN1-Notch-Hes1 interaction in the skin and melanoma development especially." (PMID 38705997, 2024). "In a previous publication, we already investigated the role of NRN1 in melanoma functionally, both in vitro and in vivo." (PMID 38705997, 2024). "We detected a retention of Notch-NICD in the cytoplasm of melanoma cells through interaction with NRN1." (PMID 38705997, 2024). "In a cohort of melanoma TCGA (The Cancer Genome Atlas) data, a high expression of NRN1 leads to a decrease in probability of survival." (PMID 38705997, 2024). "Trying to elucidate the molecular mechanisms of NRN1 signaling in melanoma cells, recent literature has established a connection with Notch signaling." (PMID 38705997, 2024). "For melanoma we showed that NRN1 is involved in regulating migration, attachment-independent growth, and vascular mimicry." (PMID 38705997, 2024). "As investigated in our previous publication NRN1 expression is higher in melanoma than in normal human epidermal melanocytes." (PMID 38705997, 2024). "The expression of NRN1 in melanoma brain metastasis is slightly elevated compared to organ metastasis." (PMID 38705997, 2024). "To establish a model system of the elevated NRN1 expression in melanoma, we generated a stable overexpression cell line using the melanoma cell line Mel JuSo (with a comparatively low NRN1 expression)." (PMID 38705997, 2024). "Using a cell culture model system with an NRN1 overexpression, we investigated the influence of NRN1 on melanoma cells’ functionality and signaling." (PMID 38705997, 2024). "In the siNRN1 knockdown, Hes1 transcription, protein levels and promoter activity were all increased, confirming the inhibitory effect of NRN1 on Notch signaling in melanoma." (PMID 38705997, 2024). "To further unravel NRN1-influenced signaling in melanoma and other malignancies, we used a pre-spotted array of important phosphorylated proteins involved in several different major cellular signaling pathways." (PMID 38705997, 2024). "In summary, these data point towards NRN1 playing an important oncogenic role in cancer, and melanoma especially." (PMID 38705997, 2024). "We therefore investigated signaling pathways that were influenced by neurotrophin NRN1, which has been shown to be upregulated in melanoma." (PMID 38705997, 2024). "Intriguingly, hypoxia-induced expression of NRN1 was also shown in melanoma cells, and soluble NRN1 induced to form vascular mimicry by melanoma cells." (PMID 34804954, 2021). "The immunohistochemical staining of a tissue microarray revealed the protein occurrence of NRN1 particularly in primary melanoma and metastases, whereas the overall impression of a stronger staining for NRN1 in primary tumors was observed." (PMID 27901477, 2017).
melanoma (continued). "In a further 3-D assay of tube formation we defined the influence of NRN1 on vascular mimicry of melanoma cells." (PMID 27901477, 2017). "For the different melanoma patient sera we classified the NRN1 values corresponding to the melanoma marker MIA." (PMID 27901477, 2017). "In the literature it was demonstrated that NRN1 can be regulated by hypoxia, a condition which is cumulative and endogenously found in melanomas." (PMID 27901477, 2017). "The migratory- and angiogenic capacity of melanoma cells was strikingly regulated by recombinant NRN1 and after silencing of endogenous NRN1, respectively." (PMID 27901477, 2017). "Silencing of NRN1 in melanoma cells led to reduced migration and attachment independent growth in 3-D soft agar assay." (PMID 27901477, 2017). "Keratinocytes of the epidermal layer were also positive for NRN1 (normal skin, and primary melanoma)." (PMID 27901477, 2017). "In this study we show that melanoma patients have significantly higher NRN1 level compared to non-melanoma patients." (PMID 27901477, 2017). "Both chemical compound simulate hypoxic effects and increase the NRN1 amount on mRNA level as exemplarily shown in the melanoma cell lines 501mel, HMB2, and Mel Im." (PMID 27901477, 2017). "To investigate the role of NRN1 in melanoma we performed knockdown, over-expression and recombinant-NRN1-treatment experiments affiliated by functional assays." (PMID 27901477, 2017). "In summary, NRN1 is expressed more extensively in melanoma than in normal melanocytes and healthy tissue." (PMID 27901477, 2017). "Our data build on previous results where NRN1 act as guidance factor for neurons and endothelial cells whereat also melanoma cells were directly guided by NRN1 to form endothelial like structures." (PMID 27901477, 2017). "In vivo three of six samples showed the double band of NRN1 in western blot analysis, one melanoma sample showed the single band of processed NRN1." (PMID 27901477, 2017). "The sub-division showed the result that patients with primary melanoma have more NRN1 in their serum compared to patients with melanoma metastases." (PMID 27901477, 2017). "This is in agreement with the detection of low expression levels of miR-204 in melanoma eventually accompanied by high NRN1 levels." (PMID 27901477, 2017). "Secreted NRN1 seems to play a role also in earlier phases of melanoma development as we can discover NRN1 over-expression to be associated to primary melanoma." (PMID 27901477, 2017). "In this context, we found NRN1 to be up-regulated in a cDNA array in melanoblast related cells (MBrc) and melanoma cell lines compared to normal human epidermal melanocytes (NHEM)." (PMID 27901477, 2017). "For the melanoma patient sera we classified the NRN1 values corresponding to the melanoma marker MIA (the relevance was mentioned in the introduction) and found a significant correlation to MIA serum levels < 10 ng/ml." (PMID 27901477, 2017). "Nevertheless, the investigation of the angiogenic activity of NRN1 on melanoma cells showed that rcNRN1 drastically induces vasculogenic mimicry of melanoma cells." (PMID 27901477, 2017). "In functional cell culture experiments we found a correlation between NRN1 expression and the cancerous behavior of melanoma cells." (PMID 27901477, 2017). "Under real hypoxic conditions of 0.2 % oxygen and 5 % carbon dioxide for 48 h the melanoma cell lines showed elevated expression level of NRN1 on mRNA and protein level which confirmed the previous results." (PMID 27901477, 2017). "This correlation suggests that circulating NRN1 may function as a novel biomarker for melanoma diagnosis or prognosis." (PMID 41425077, 2025). "Since we could already show this overexpression of NRN1 in melanoma, we used an intracellular overexpression system to elucidate some of the signaling pathways and cellular functions NRN1 is involved in." (PMID 38705997, 2024).
melanoma (continued). "Considering the fact that in our model system of high NRN1 expression in melanoma we saw a direct binding of NRN1 to N1ICD and N3ICD, we hypothesize a retention of the Notch intracellular domains in the cytoplasm through NRN1." (PMID 38705997, 2024). "In summary, we detected an overexpression of NRN1 in melanoma patient." (PMID 27901477, 2017). "To extend our experiments, we further analyzed NRN1 mRNA expression level from in situ microdissected tissue from melanoma patients (5 primary, 6 lymph node- and 9 visceral metastases) and compared the expression status with NHEMs and microdissected epidermis from normal skin (altogether 7 donors)." (PMID 27901477, 2017). "We defined the NRN1 secretion in 113 melanoma and 57 normal patient sera." (PMID 27901477, 2017). "Eventually, secreted NRN1 is usable as serum marker for early melanoma." (PMID 27901477, 2017). "The melanoma patients harbor significant higher NRN1 levels compared to non-melanoma patient." (PMID 27901477, 2017). "Our newest findings document that NRN1 deregulation could contribute also to disease development and have impact on malignant melanoma." (PMID 27901477, 2017). "Our analyses displayed the over-expression of NRN1 in melanoma in vitro and in vivo, shown by immunohistochemistry and qRT-PCR on microdissected melanoma tissue; furthermore, soluble NRN1 was detectable in tissue culture supernatant and serum of melanoma patients." (PMID 27901477, 2017). "The deduction is that low miR-204 levels in melanoma allow a high expression rate of NRN1." (PMID 27901477, 2017). "Both treatment strategies for melanoma cells led to elevated NRN1 expression levels." (PMID 27901477, 2017). "Therefore, we used first an ELISA to quantify NRN1 in the supernatant of different melanoma cells and detected elevated NRN1 levels compared to NHEM." (PMID 27901477, 2017). "We also aimed at detecting the NRN1 double band in protein lysates of melanoma tissue." (PMID 27901477, 2017). "Interestingly, we found also chemotactic influences of soluble NRN1, as the induction of vascular structures by melanoma cells in angiogenesis assays." (PMID 27901477, 2017). "After sub-cloning NRN1 into the eukaryotic expression vector pCDNA3 we stably transfected the melanoma cell line Mel Ju and proved the over-expression on mRNA and protein level in two different cell clones (NRN1_a and NRN1_b) compared to two controls (ctrl a and ctrl b)." (PMID 27901477, 2017). "Therefore, we used recombinant NRN1 to prove its effectiveness to regulate tumor-promoting effects on melanoma cells." (PMID 27901477, 2017). "To evaluate whether malignant transformation affects the expression of NRN1, we analyzed NRN1 in melanoma cells both at the mRNA and at the protein level." (PMID 27901477, 2017). "An ELISA and Western blot analysis detect secreted NRN1 in several melanoma cell lines." (PMID 27901477, 2017). "Interestingly, the baseline NRN1 values in healthy donors ranged from ~20 to ~390 pg/ml and NRN1 was significantly elevated in the melanoma patient sera (max 915 pg/ml) compared to the healthy individuals." (PMID 27901477, 2017). "Interestingly, there also seems to be a connection between NRN1 and melanoma brain metastasis." (PMID 38705997, 2024). "What could be shown in vivo, is an upregulation of NRN1 mRNA levels from nevi to primary melanoma." (PMID 38705997, 2024). "Therefore, NRN1 seems to play a role in early melanoma development." (PMID 38705997, 2024). "Notably, soluble NRN1 promotes the migration of melanocyte cells and higher serum NRN1 levels were observed in melanoma patients compared with healthy donors, indicating that soluble NRN1 may also be a potential diagnostic biomarker in RCC patients." (PMID 34804954, 2021). "Therefore, in this study we analyze the role of NRN1 in the biology of melanoma." (PMID 27901477, 2017). "Therefore, we analyzed the occurrence of soluble NRN1 in the supernatant of melanoma cells." (PMID 27901477, 2017).
melanoma (continued). "The results suggest that NRN1 expression may be part of oncogenic signaling pathways in melanoma." (PMID 27901477, 2017). "Our latest research results link the functions of intracellular NRN1 to the Notch and STAT3 signaling pathways in melanoma." (PMID 38705997, 2024). "In summary, we were able to show that NRN1 links oncogenic signaling events between Notch and STAT3 in melanoma." (PMID 38705997, 2024). "Further, we validated the occurrence of soluble NRN1 by western blot analysis of supernatants of NHEM and melanoma cell lines and confirmed the ELISA result." (PMID 27901477, 2017). "In particular, the expression of a newer member of the neurotrophin family, NRN1 (cpg15), is differentially regulated between NHEM and melanoma cell lines which is shown for the first time by our analysis on mRNA and protein level." (PMID 27901477, 2017). "Therefore, we speculate that NRN1 could be a marker for early melanoma stages, in particular." (PMID 27901477, 2017). "Importantly, the increased in vivo expression of internal NRN1 in primary melanoma and metastases versus normal or nevi tissue was also detectable by our research of laser-micro-dissected melanomas of patient and by immunohistochemistry analysis of melanoma samples." (PMID 27901477, 2017). "Previous data also showed that there was no clear correlation between NRN1 protein levels and tumor stage in melanoma." (PMID 38705997, 2024). "Two melanoma samples were negative for NRN1 and two normal skin protein lysates (N) were also negative for NRN1." (PMID 27901477, 2017). "Recombinant (rc) NRN1 does not regulate endogenous NRN1 expression level or the proliferation rate and short time (~30 min) attachment of melanoma cells." (PMID 27901477, 2017). "We show that NRN1 is nearly not expressed in normal human melanocytes (NHEM) but melanoma cells showed an elevated NRN1 expression level." (PMID 27901477, 2017). "Unfortunately, cancer survival data from melanoma patients to consider the role of NRN1 in our experimental set were not available to us." (PMID 27901477, 2017). "Unfortunately, because of ethical guidelines it was not possible to get survival information from melanoma patients considering NRN1." (PMID 27901477, 2017). "No receptor for NRN1 has yet been discovered in melanoma either." (PMID 38705997, 2024). "Whether the NRN1 expression level is also regulated by miR-204 in melanoma was not further analyzed by us." (PMID 27901477, 2017). "To analyze whether NRN1 actually exerts any function on melanoma cells, we decided to focus our attention on three melanoma cell lines: HMB2, 501mel, and Mel Im which are well known in the melanoma research field and show high expression levels of NRN1." (PMID 27901477, 2017). "Here, the melanoma cells in the assay were kept in fresh DMEM medium, hence the medium was not already enriched with (cellular)-secreted NRN1." (PMID 27901477, 2017). "Furthermore, a cDNA array comparing three primary melanomas and three melanoma metastases with NHEM showed that NGF, NT-3, NT-4, BDNF, and NRN1-like are not differentially regulated and only NRN1 is ~48-fold elevated in melanoma compared to NHEM." (PMID 27901477, 2017).
breast cancer (5 papers, 2017 to 2025). A primary or metastatic malignant neoplasm involving the breast. "Analysis of these TCGA datasets (using PRISURV) revealed longer survival of breast cancer, lung cancer, and cervical cancer patients with high as compared to low NRN1 expression." (PMID 27901477, 2017). "In breast cancer the promoter of cpg15 (nrn1) was found to be hyper-methylated." (PMID 27901477, 2017). "However, we used PRISURV as bioinformatics tool uncovering the role of NRN1 in different cancer entities and found a positive correlation of high NRN1 expression levels with cancer survival outcome of breast cancer, lung cancer, and cervical cancer patients supporting our data." (PMID 27901477, 2017).
depression (5 papers, 2022 to 2025). "Previous studies have identified ELAVL4 as an RBP targeting several neuroplasticity-related mRNAs, including Bdnf, Ngf, Gap-43, and Nrn1, all of which are closely associated with neuroplasticity and have well-established links to depression." (PMID 39940881, 2025). "Neuritin 1 is associated with mental illness, such as schizophrenia, bipolar disorder and depression." (PMID 36765573, 2023). "NRN1’s ability to counteract stress, along with its connections to serotonergic neural networks, emphasizes its potential for future treatments of anxiety and depressive disorders." (PMID 41425077, 2025). "In this sense, we found a significant interaction between NRN1-rs10484320 and BDNF-rs6265 impacting PANSS general psychopathology, which encompasses symptoms like anxiety, guilt, tension, depression, and disorientation." (PMID 38720004, 2024).